STAT3 (signal transducer and activator of transcription 3)
Diseases named in the same sentence as STAT3 in open-access papers (continued):
Sharing a sentence is not in itself a finding about the gene and the disease.
prostate carcinoma (continued). "Inhibition of JAK/STAT3 signaling by gene silencing or using an IL-6 receptor fusion protein (IL-6RFP), which acts as a cytokine trap to sequester soluble IL-6, exhausts the CSC population in both murine and human prostate cancer models." (PMID 26880966, 2016). "Although STAT3 and IL6 have a definite impact on prostate cancer, because of the intrinsic molecular heterogeneity of prostate cancer, their role might be condition and stage dependent." (PMID 28005952, 2016). "Specifically, this study showed that multiple cancer cells (e.g., lymphoma, adenocarcinoma, breast and prostate cancer) maintain activated STAT3 persistently via SIP-S1PR1 signaling, without IL6-GP130 signaling." (PMID 26173622, 2015). "While both NF-κB and STAT3 are well known mediators of prostate carcinogenesis and progression, their collaboration in promoting prostate cancer-propagating cells has not yet been shown." (PMID 26046794, 2015). "In prostate cancer cells, the interaction of CCL2 and CCR2 induced STAT3 activation." (PMID 25405202, 2014). "IL-6 can convert non-ALDHhigh cells to ALDHhigh cells in prostate cancer cell line as well as from cells derived from human prostate tumors, the conversion mediated by IL-6 was abrogated in the presence of STAT3 inhibitor or upon STAT3 knockdown." (PMID 25261365, 2014). "Third, in prostate cancer and chronic lymphocytic leukemia, phosphorylation of STAT3Ser727 rather than STAT3Y705 was found to be crucial for the nuclear translocation, DNA binding and the tumor-promoting function of STAT3." (PMID 24995504, 2014). "Previously, we have proposed our hypothesis that glucosamine could inhibit the N-glycosylation of IL-6 receptor in human prostate carcinoma DU145 cells, thereby reducing the activity of the IL-6/JAK/STAT3 signaling pathway." (PMID 24932134, 2014). "NF-kB and STAT-3 (phosphorylated form of STAT-3) transcription factors and Androgen Receptor (AR) play a critical role in cell proliferation, anti-apoptosis, angiogenesis and invasion of prostate cancer cells." (PMID 23824300, 2013). "Furthermore, gene expression analysis of prostate cancer stem cells has revealed a pro-inflammatory phenotype and that the JAK/STAT3-signaling pathway is active in this cell population." (PMID 21779382, 2011). "Signal transducer and activator of transcription 3 (STAT3) is an important transcription factor in many cancer types and it has been shown to be involved in drug resistance and to have anti-apoptotic effects in prostate cancer cells." (PMID 21779382, 2011). "STAT3 is also known to promote androgen-independent growth in cultured prostate cancer cells, giving additional support to the beneficial effect of PLA2G7 inhibition in prostate cancer management." (PMID 22202492, 2011). "Thus, in the present study, we investigated the roles of STAT3 and HIF-1 α in BA induced anti-angiogenic activity in hypoxic PC-3 prostate cancer cells by MTT assay, Western blotting, immunocytochemistry, ELISA and EMSA." (PMID 21731766, 2011). "Additional analysis using the GEO database determined that both Sox1 and Stat3 are expressed at higher levels in metastatic prostate cancer tissues and not Bmx." (PMID 20929579, 2010). "The results together, indicated that STAT3 could be a targeted critical element in the EGF-mediated cell migration and invasion of prostate carcinoma cells." (PMID 16804520, 2006). "As we have previously shown that prostate carcinoma cells present autocrine EGFR signalling, we determined whether this also invoked STAT3 activation." (PMID 16804520, 2006). "In this study, we investigated whether activated STAT3 protein is involved in the EGF-receptor-mediated migration in fibroblasts and human prostate cancer cells and the invasiveness of the latter." (PMID 16804520, 2006). "STAT3 is negatively regulated by a retinoid-sensitive protein, GRIM-19, which may explain the positive effects retinoids show against prostate cancer cells in vitro." (PMID 15647107, 2005).
prostate carcinoma (continued). "Dysbiosis in the gut microbiota had been shown to promote the progression of prostate cancer in antibiotic exposure mice via the Toll-like receptor 4 (TLR4) activated transcription factor-κB (NF-κB)—interleukin (IL)−6- signal transducer and activator of transcription 3 (STAT3) axis." (PMID 40576719, 2025). "Western blot analysis showed that LINC00467 could regulate the STAT3 pathway, and bioinformatics analysis and salvage experiments indicated that LINC00467 promoted prostate cancer progression and mediated the transformation of prostate cancer to NEPC through the miR-494-3p/STAT3 axis." (PMID 39655078, 2024). "In summary, this work elucidates NCAPD3 inhibits miR-30a-5p through two pathways: increasing STAT3-MALAT1 to sponge miR-30a-5p and increasing MYC to directly inhibit miR-30a-5p transcription, which could serve as potential therapeutic targets for prostate cancer." (PMID 38561330, 2024). "Indeed, we found that the number of clusters expressed by specific combinations of either intra-vesicular (STAT3 and CyclinD1) or surface proteins (ERBB3, ALK, and CD81) allowed us to significantly discriminate the patients with prostate cancer from the individuals with hyperplasia." (PMID 39120316, 2024). "Hence, STAT-3 inhibition by STT has been reported to increase apoptosis in several in vitro studies on nasopharyngeal, esophageal, ovarian, and prostate cancer cell lines, as well as in vivo xenograft models of colorectal cancer, diffuse large B-cell lymphoma, and prostate cancer." (PMID 39329957, 2024). "ATL II also suppresses the proliferation and induces death of human prostate cancer cells DU145 and LNCaP, and arrests the cell cycle in the G2/M phase through mechanisms that possibly relate to AR inhibition, PIAS1 activation, and inhibition of the JAK2/STAT3 signaling pathway." (PMID 37241729, 2023). "Furthermore, in prostate cancer, it facilitates M2 polarization via the SOCS3/STAT3 pathway." (PMID 37759870, 2023). "Indeed, the IL-6/STAT axis represents a link between inflammation and prostate carcinogenesis, which is the signal transducer and activator of transcription 3 (STAT3), a key modulator in the expression of a wide range of oncogenic genes and a player in prostate cancer energy." (PMID 36982868, 2023). "However, the proliferation in the STAT3-negative PC-3 prostate cancer cell line did not change after STAT3 siRNA application." (PMID 38067351, 2023). "As a conclusion, one may say, that the treatment of androgen-independent prostate cancer cells with SAM leads to the downregulation of the ERK1/2 pathway and STAT3 pathways which both are involved in cell survival, proliferation, migration and invasion of cancer cells." (PMID 35303200, 2022). "In localized and metastatic castration-resistant prostate cancer patients, treatment with TLR9-targeted STAT3 siRNA delivery to abrogate the immunosuppressive function of MDSCs diminished the enzymatic activity of Arg-1, inhibited STAT3 target gene and T cell function." (PMID 36246629, 2022). "Additionally, the development of prostate carcinoma could be promoted by LINC00467 through the microRNA-494-3p/signal transducer and activator of the transcription 3 (STAT3) axis." (PMID 35587748, 2022). "We have demonstrated that the small molecule STAT3 inhibitor galiellalactone inhibits the prostate cancer cell induced generation of monocytes with a myeloid-derived suppressor cell (MDSC)-like phenotype and immunosuppressive factors in both human prostate cancer cells and immune cells ex vivo." (PMID 33786638, 2021). "In addition, in LNCaP prostate cancer cells, hydroxytyrosol inhibited cell proliferation in a concentration dependent manner (IC50 = 176 μM 48 h post treatment) through the suppression of Akt/STAT3 phosphorylation and by the cytoplasmic retention of NF-κB." (PMID 33430068, 2021).
prostate carcinoma (continued). "Via a non-canonical pathway, EZH2 methylates and activates STAT3 (Signal Transducer And Activator Of Transcription 3), acts as a co-activator for androgen receptor (AR) in castration resistant prostate cancer and enhances cellular proliferation via the E2F pathway." (PMID 33246425, 2020). "Moreover, aberrant activated STAT3 was found in prostate cancer tissues but not in the normal tissues." (PMID 33094561, 2020). "However, CRIF1 binding and co-activation of STAT3 may counteract the AR repressor effect of CRIF1, thus sustaining prostate cancer cell growth." (PMID 29914167, 2018). "RKIP overexpression in breast and prostate cancer cell lines was shown to inhibit cellular Src (c-Src) autophosphorylation and activation, as well as interleukin 6 (IL-6)-, janus kinase 1/2 (JAK1/2)-, and activated Raf-mediated STAT3 tyrosine and serine phosphorylation, needed for STAT3 activation." (PMID 30149591, 2018). "However, while IFN robustly induced miR-21 expression in DU145 prostate cancer cells, IFN did not induce miR-21 expression in PC3 prostate cancer cells that have a genetic deletion of the STAT3 locus." (PMID 26610525, 2015). "However, the breadth and scope of STAT3 regulatory networks that drive the progression of prostate cancer (PCa) have not been addressed recently." (PMID 24722453, 2014). "Hence, in the present study it can be postulated that piperine can induce apoptosis by inhibiting the activation of phosphorylated STAT-3 in LNCaP, DU145 and PC-3 cells which, in turn, may inhibit the survival and growth of prostate cancer cells." (PMID 23824300, 2013). "However, not all prostate cancer cell lines that are sensitive to M-110 treatment express activated STAT3." (PMID 22193779, 2011). "Interestingly, dasatinib treatment of both lung and prostate cancer-derived cell lines did not affect pStat3 levels, suggesting that Src inhibition does not play a role in mediating Stat3 activation in these cancer-derived cell lines." (PMID 17531096, 2007). "Thus, JAK2 and STAT3 may not directly contribute to prostate cancer progression but could modulate the immune tumor microenvironment, thereby promoting disease development." (PMID 40978029, 2025). "Interestingly, the suppression of STAT3 activation by sulforaphane seems to be not cell type restricted, and, supporting our results, was recently reported in vascular endothelial cells, liver, nasopharyngeal, and prostate cancer cells." (PMID 33193420, 2020). "Given the dramatic increase in the survival of prostate tumor cells in HGFL+/+ TRAMP+ mice compared to those without HGFL, we next sought to examine whether STAT3 activation acts as a survival mechanism downstream of Ron signaling in prostate cancer cells ex vivo." (PMID 24980820, 2014). "Primary human prostate cancer cells and prostate cancer cell line contained high aldehyde dehydrogenase activity (ALDHhigh) subpopulations with stem cell-like characteristics, which expressed higher levels of the active phosphorylated form of STAT3 (pSTAT3) than that of non-ALDHhigh subpopulations." (PMID 25261365, 2014). "The results of a recent study suggested that extracellular PRL enhanced NSCLC cell proliferation and promoted JAK2/STAT3 signaling activity through GHR, but not PRLR as previously reported in breast and prostate cancers." (PMID 34487971, 2021). "However, whether it can suppress prostate cancer through STAT3 is not yet elucidated." (PMID 32784629, 2020). "However, despite the positive data in preclinical models, the clinical activity in advanced prostate cancer patients was modest or not significant, suggesting that anti-IL-6 therapies may not be the most effective approach to block STAT3 signaling in this setting." (PMID 31143708, 2019).
prostate carcinoma (continued). "Meanwhile, a novel mechanism that IL-6 promoted prostate cancer metastases through a soluble IL-6 receptor (sIL-6R) without activation of STAT1, STAT3 or MAPK was also documented." (PMID 26528698, 2015). "As a STAT3 negative control cell line, we used in our experiments the prostate cancer line PC3, which is homozygous STAT3 null." (PMID 22315522, 2012). "Additionally, in prostate cancer (DU45) and pancreatic cancer (MiaPaCa-2) cell lines, PIM3 specifically, but not PIM1 and PIM2, regulates p-STAT3 levels, potentially through its protein tyrosine phosphatase and tyrosine kinase activity." (PMID 38339286, 2024). "Using the STAT3 small molecule inhibitor, Stattic, which has been shown to selectively inhibit the function of the STAT3 SH2 domain regardless of STAT3 phosphorylation status, we showed that Stattic potentially prevented phosphorylation of STAT3 in prostate cancer cells." (PMID 25261365, 2014). "However, whether Osthole exerts its anticancer effects in prostate cancer by modulating PRLR and the JAK2/STAT3 signaling axis has not been thoroughly investigated." (PMID 40978029, 2025).
melanoma (710 papers, 2007 to 2026). A malignant, usually aggressive tumor composed of atypical, neoplastic melanocytes. "Deleting IκBζ in melanoma abrogates the activity and chromatin association of STAT3 and NF-κB, thereby reducing the expression of the pro-proliferative cytokines IL-1β and IL-6, thus impairing melanoma cell growth." (PMID 40562773, 2025). "Previous studies have indicated that the expression of phosphorylated STAT3 (p-STAT3) in melanoma cells is associated with poor prognosis." (PMID 40519928, 2025). "In melanoma, poor prognosis and unfavorable clinicopathological features are associated with STAT3 hyperactivation." (PMID 40399946, 2025). "IFN-γ is known to activate STAT3, a nuclear transcription factor implicated in playing an essential role in the development and progression of melanoma." (PMID 39941844, 2025). "In summary, constitutively expressed IκBζ in melanoma stabilizes specific promoter binding and chromatin association of STAT3, p65, and potentially STAT1, depending on the specific target gene." (PMID 40562773, 2025). "Clinical trials have shown that SFN (200 μmol) modulates STAT3 in cancer cells, thereby preventing skin cancer and melanoma caused by ultraviolet light." (PMID 38671854, 2024). "The activation of both c-Abl and Arg kinases in human primary melanomas is associated with melanoma cell invasion via a mechanism mediated by Stat3." (PMID 39123481, 2024). "For example, the IL6 induced STAT3 pathway is linked to an EMT signature in melanoma and its activation reduced the cell cycle as well as the differentiation associated pigmentation pathway." (PMID 38902533, 2024). "The delivery of STAT3 siRNA to B16 melanoma cells using these nanoparticles was very effective and caused a reduction in STAT3 expression and an induction of cell apoptosis." (PMID 38067351, 2023). "Mice with STAT3-deficient NK cells are significantly decreased in the metastasis of B16F10 melanoma." (PMID 37501379, 2023). "Exosomal miR-155-5p secreted by melanoma cells can induce the proangiogenic switch of cancer-associated fibroblasts (CAFs) via the SOCS1/JAK2/STAT3 pathway." (PMID 37248542, 2023). "Intriguingly, suppression of STAT3 signaling with DR-1-55 in HLA-G OE BMICs caused a drastic decline in the secondary sphere formation of HLA-G OE lung and melanoma BMICs despite the presence of high HLA-G levels in these cells." (PMID 36780531, 2023). "Increased studies have observed that secretomes obtained from TIS senescent melanoma cells activated the STAT3 pathway, causing melanoma cells to transition into a mesenchymal phenotype, which facilitates chemoresistance and recurrence behaviors." (PMID 37174106, 2023). "The abnormally high levels of Stat3 activity have been associated with an increased likelihood of melanoma returning after treatment." (PMID 37375842, 2023). "In contrast to STAT3 in prostate tumors, STAT3 inhibition decreased the effect of NDV on melanoma cells, further reducing the release of ICD-associated DAMPs." (PMID 36466838, 2022). "NK cell-intrinsic STAT3 deficiency is sufficient to increase surveillance of melanoma and leukemia cell lines." (PMID 35865518, 2022). "STAT3 has also been implicated in the regulation of many genes that contribute to the signaling pathways in melanoma survival and proliferation." (PMID 35105915, 2022). "This pathway is hyperactive in many types of cancers, including melanoma, and hyperactivation of STAT3 in tumor‐infiltrating immune cells is associated with an immunosuppressive effect." (PMID 36176603, 2022). "STAT3, as a point of convergence of many signaling pathways, has been implicated in melanoma progression." (PMID 34680615, 2021). "We have previously shown that RNLS is present in tumor-associated macrophages adjacent to melanoma, which can promote tumor growth through a STAT3-mediated mechanism." (PMID 34587190, 2021).